TNF (tumor necrosis factor)
Diseases named in the same sentence as TNF in open-access papers (continued):
Sharing a sentence is not in itself a finding about the gene and the disease.
periodontal disease (continued). "The possible effect of TNF-α gene promoter polymorphism on the periodontal disease severity and clinical outcome remains to be elucidated." (PMID 29449347, 2018). "According to our ELLSA results, curcumin inhibited the production of IL-1β and TNF-α in rat gingival fibroblasts induced by LPS, which showed that curcumin has potential role in modulating immune response associated with periodontal diseases." (PMID 30115081, 2018). "In periodontal disease, increased inflammation and bone loss is modulated by the proinflammatory cytokines Il-1, Il-6, and TNF-α." (PMID 24130702, 2013). "The present survey showed that the prevalence of CKD was 18.2% in patients with periodontal disease, with low awareness of 16.2%, and inflammation markers (IL-6, hsCRP or TNF-α) are special risk factors for CKD in this population." (PMID 23951003, 2013). "Bacterial pathogens causing periodontal disease incite the secretion of inflammatory mediators, including IL-6, TNF-α and CRP." (PMID 23951003, 2013). "Subsequently, several inflammatory factors, including IL-17 and TNF, along with associated pathological conditions such as overweight and coronary atherosclerosis, were identified as key mediators in the causal pathway from periodontal disease to AF." (PMID 39988492, 2025). "Considering the modulatory role of CTRP-1 in inflammation, analyzing its association with inflammatory mediators like TNF-α and IL-10 in periodontal disease may offer important perspectives on disease progression and potential interventions." (PMID 40542868, 2025). "Studies have reported elevated levels of pro-inflammatory cytokines (e.g., IL-10, IL-12, TNF-α) in e-cigarette users, which may contribute to microbiota dysbiosis and an increased risk of periodontal diseases." (PMID 40559585, 2025). "Elevated TNF-α levels are strongly associated with periodontal disease severity." (PMID 40542868, 2025). "Elevated levels of C-reactive protein and pro-inflammatory cytokines like TNF-α and IL-6 induced by periodontal disease are linked to systemic disorders and could indirectly affect both the lungs and the brain." (PMID 38909262, 2024). "The improvement in BOP may be due to RSV’s anti-inflammatory effect, which reduces the release of proinflammatory cytokines (IL-1, IL-6, and TNF-α) implicated in the pathophysiology of periodontal disorders." (PMID 41328922, 2024). "Previous studies have shown that elevated levels of serum inflammatory markers, such as tumor necrosis factor-α, interleukin-6, interleukin-2, and C-reactive protein, are associated with an increased risk of AF and are commonly found in patients with periodontal disease." (PMID 37420240, 2023). "Several clinical trials have shown an association between salivary TNF and periodontal diseases." (PMID 36845132, 2023). "Furthermore, in T2DM there is an increase in TNF-α, IL-1β, IL-6, and IL-18, which are known to elevate HbA1C, which increases the risk for periodontal disease." (PMID 37629193, 2023). "Similarly, TNF-α adversely affects the immunity of the body, especially in periodontal tissue that possibly acts as a risk factor for periodontal disease." (PMID 36231983, 2022). "Periodontal disease is associated with increases in the levels of lipopolysaccharides (LPS) and cytokines such as tumor necrosis factor alpha and interleukin 1, and these cytokines may have a negative effect on lipid metabolism." (PMID 34199827, 2021). "Furthermore, periodontal disease found to be associated with increased TNF-α secretion in oral blood immune cells." (PMID 33672708, 2021). "In addition, patients with periodontal disease are shown to have genetic predisposition for increased cytokine secretion, particularly IL-1β and TNF-α." (PMID 33672708, 2021).
periodontal disease (continued). "Several studies also show the relationship between sex hormones and changes in the production of inflammatory cytokines such as tumor necrosis factor, which has been quite associated with periodontal disease, as well as the IL-1 and IL-6, associated with bone resorption." (PMID 33526027, 2021). "Pro-inflammatory cytokines such as IL-1β, IL-6, and TNF-α produced by monocytes, macrophages, and fibroblasts stimulated by pathogenic factors of periodontal pathogens contribute to the progress the periodontal disease as well as systemic diseases such as diabetes and rheumatoid arthritis." (PMID 30574217, 2018). "Notably, serum TNFα levels are known to be increased with aging and are associated with age-related diseases such as periodontal disease." (PMID 29464018, 2018). "Therefore, if the susceptibility of HGFs to TNF-α has been enhanced by butyric acid stimulation, there is a high possibility that the progression of periodontal disease pathology is promoted by butyric acid." (PMID 30574217, 2018). "We hypothesized that the genetic variation affecting the expression or activity of TNF-α influences the susceptibility and severity of periodontal disease." (PMID 29449347, 2018). "Cytokine participation in periodontal disease is well documented and these substances, particularly TNF-α and IL-1β, may amplify the inflammatory response causing tissue destruction and bone loss." (PMID 27116554, 2016). "Therefore, we can exclude smoking and periodontal disease as a potential causes of differences between IL-6 and TNF-α serum concentration between men and women." (PMID 25858079, 2015). "The main problem related to periodontal disease is bone loss, which is caused by activation of lymphocyte pro-inflammatory cytokines, such as IL-1β and TNF-α, and may be mediated by significant increases in IL-10 levels." (PMID 24819928, 2014). "For example, one could screen the GCF TNF-α levels of obese individuals to identify a subgroup of obese subjects, who are more susceptible to develop destructive periodontal disease." (PMID 24068858, 2013). "Elevated levels of TNF-α are a well-known risk factor for destruction periodontal disease." (PMID 24068858, 2013). "We found that high values of hsCRP and TNF-α level were associated with the albuminuria in patients with periodontal disease; high value of IL-6 level was associated with the reduced eGFR in patients with periodontal disease; high value of TNF-α level were associated with the CKD." (PMID 23951003, 2013). "The C allele of VEGF, a regulator gene of angiogenesis and lymphangiogenesis, the A allele of IL-10, an anti-inflammatory gene and the GG genotype of TNF, a gene involved in both inflammation and bone remodeling, were associated with an increased risk of periodontal disease." (PMID 24274085, 2013). "It has been described that the release of interleukin (IL) 1 beta (IL-1B) and tumor necrosis factor alpha (TNF-A), inhibit leukocyte trafficking and attenuate the inflammatory reactions caused by Porphyromonas gingivalis, gives strength to the potential protective role in periodontal disease." (PMID 37629298, 2023). "Thus, the association between TNF-α in saliva and periodontal disease might depend upon the health status of the study subjects and the severity and progression of periodontal disease." (PMID 34199256, 2021). "The associated pathophysiology could be that periodontal disease induces host cells to generate and release pro-inflammatory cytokines such as interleukin-1 (IL-1), interleukin-6 (IL-6), tumor necrosis factor-alpha (TNF-α), and reactive oxygen species (ROS) to induce the development of PD." (PMID 30049978, 2018). "Hence, TNF-α is present during periodontal disease-associated bone resorption." (PMID 24151615, 2013). "In periodontal diseases, MMP-9 and IL-6 play roles in inflammatory-driven bone loss, while TNF-α and TRAP (ACP5) are implicated in osteoclast activation." (PMID 41559024, 2026).
periodontal disease (continued). "This suggests a significant involvement of TNF-α in the pathogenesis of periodontal disease, contributing to tissue destruction and exacerbating the inflammatory process." (PMID 41280962, 2025). "Targeting these shared axes—whether through the modulation of autophagy, inhibition of TNF or IL-6 signaling, or fine-tuning of Wnt pathways—represents a promising translational strategy for controlling chronic inflammation and preventing bone loss in periodontal disease." (PMID 41155385, 2025). "Although elevated ESM-1 levels have been observed in various systemic inflammatory diseases, its role in periodontal disease, particularly in relation to established markers like TNF-α and VEGF-A, remains insufficiently explored." (PMID 40426985, 2025). "ROC analyses have shown that both TNF-α and IL-10 exhibit high AUC value, supporting their utility as biomarkers in periodontal disease status." (PMID 40542868, 2025). "Worth mentioning, in periodontal diseases, dynamic changes in the level of LPS and consequently cytokines such as IL-1 beta and TNF-alpha results an increased level of the collagen degrading enzymes MMP-9." (PMID 40281482, 2025). "This study assessed the levels of ESM-1, VEGF-A, and TNF-α in GCF in the context of periodontal disease prior to and following NSPT." (PMID 40426985, 2025). "The correlations between GCF VEGF-A, ESM-1, and TNF-α levels and periodontal disease were also assessed." (PMID 40426985, 2025). "Nevertheless, the findings regarding TNF-α and IL-10 are consistent with those of prior research on inflammatory biomarkers in periodontal disease." (PMID 40542868, 2025). "Several pro-inflammatory interleukins, notably IL-1β, IL-6, TNF-α, and IL-17, have been proposed as biomarkers for periodontal disease." (PMID 41155385, 2025). "Periodontal disease involves the chronic production of inflammatory cytokines, such as TNF-α, IL-1β, IL-6, IL-8, and IL-17, which contribute to the destruction of soft and hard tissues." (PMID 40867800, 2025). "Our results were in agreement with the results of other authors who found high concentrations of TNF-α in the gingival fluid of patients with periodontal diseases." (PMID 40002575, 2025). "Specifically, the reduction in TNFα was significant only in the gingivitis subgroup (p = 0.02), while IFNγ showed a consistent and highly significant decrease across all stages of periodontal disease (p < 0.0001 for all comparisons)." (PMID 41280935, 2025). "Tumor necrosis factor-alpha is among the first proinflammatory cytokines released in periodontal disease." (PMID 40997031, 2025). "A three-group meta-analysis showed that immunotherapy affected periodontal disease progression by modulating local immune factors IL-1β, IL-17, IL-6, IL-8 and TNF-α, thus providing a potential statistically significant benefit." (PMID 41356100, 2025). "(2024) successfully demonstrated significant reductions in TNF-α and IL-6 at 8 weeks in diabetic patients with periodontal disease." (PMID 41244040, 2025). "The treatment also reduced the production of some biological mediators of periodontal disease such as tumor necrosis factor alpha and nitric oxide." (PMID 40332414, 2025). "In particular, IL-1β and TNF-α are the most extensively studied and are strongly correlated with the development of periodontal disease." (PMID 41154468, 2025). "The correlation between periodontal disease and elevated levels of TNF-α suggests that it serves as a key mediator in the local bone degradation observed in this condition." (PMID 38920850, 2024). "The constant stimulation by the dental biofilm keeps a constant stimulation of TNF-α levels in periodontal disease, resulting oedema, vasodilatation, recruitment of cells, and finally tissue destruction." (PMID 38256582, 2024).
periodontal disease (continued). "Periodontal disease induces chronic inflammation, releasing pro-inflammatory cytokines like IL-6, TNF-α, and CRP, which exacerbate neuroinflammation, disrupt the blood–brain barrier, and promote neurodegeneration." (PMID 39768299, 2024). "Periodontal disease, compared to the controls, triggered an increase in inflammatory cytokines (IL-6, TNF-α) in the uterus and oral cavity, which was abrogated by nisin treatment." (PMID 39203489, 2024). "The RT-qPCR results indicated a significant increase in the expression of key proinflammatory cytokines, such as IL-1β, TNF-α, and IL-6, in brain tissues as a result of Pg-induced periodontal disease." (PMID 38892314, 2024). "Periodontal disease triggered higher levels of inflammatory cytokines (IL-6, TNF-α) in the uterus, which was abrogated by nisin treatment." (PMID 39203489, 2024). "Catechins have shown inhibitory properties of pro-inflammatory cytokines, interleukins IL-1β and IL-6, and tumor necrosis factor (TNF) in patients with active periodontal disease, with benefits including inflammation regression and bone resorption." (PMID 39452941, 2024). "There were also highly statistically significant differences in interleukin 8 and TNFα levels between the two stages of periodontal disease." (PMID 38920850, 2024). "Periodontal disease triggered an increase in inflammatory cytokines (IL-6, TNF-α) in the uterus, which was abrogated by nisin treatment." (PMID 39203489, 2024). "These arguments are based on the fact that TNF-α, IL-1, and IL-6 are produced in large quantities in adipose tissue and as a result of periodontal disease." (PMID 39337292, 2024). "Several cytokines have a recognized role in the pathogenesis of periodontal disease including interleukin-1(IL-1), interleukin-6 (IL-6), tumor necrosis factor- α (TNF- α) and vascular endothelial growth factor (VEGF)." (PMID 38671416, 2024). "Our results showed that TNFα and IL-6 production levels were significantly increased in patients with periodontal disease in comparison with HC." (PMID 36599866, 2023). "Demonstration of the role of TNF-α in bone resorption by increasing osteoclastic activity and deceasing osteoblastic activity has shared relevance to both periodontal disease and OSCC." (PMID 36980727, 2023). "Among these secreted cytokines, especially tumor necrosis factor‐alpha (TNF‐α), interleukin (IL)‐1 (β and α), and IL‐6 are important for the development of periodontal disease." (PMID 37970391, 2023). "Inflammatory mediators released from periodontal disease, such as interleukin-6, tumor necrosis factor-alpha, and prostaglandin E2, can escape through damaged periodontal tissue pockets and produce systemic effects elsewhere in the body." (PMID 37509588, 2023). "RANKL, TNF-α, IL1-β, and other cytokines, implicated in both the pathogenesis of periodontal disease and osteoporosis, would stimulate the continuous production of osteoclasts by progenitor cells, initiating bone destruction and inflammation." (PMID 37214190, 2023). "Increased levels of TNF-α has also been highlighted as a link between periodontal disease and Diabetes Mellitus, as well as other inflammatory conditions such as rheumatoid arthritis." (PMID 36980727, 2023). "LPS administration into experimental animals causes massive secretion of TNF-α and other endogenous inflammatory mediators which are associated with clinical symptoms of SLE and periodontal diseases." (PMID 38069267, 2023). "These salivary cytokines, particularly IL-1β, IL-6, and TNF-α, offer reliability in assessing the severity of periodontal disease, making them valuable markers for monitoring disease progression." (PMID 38192959, 2023). "TNF is considered a key biomarker that reveals insights about diagnosis, prognosis, and treatment in periodontal disease." (PMID 36845132, 2023).
periodontal disease (continued). "As a result of the host-mediated immune response to this microbial challenge, serum concentrations of inflammatory mediators, including interleukin-1β (IL-1β), tumor necrosis factor-α (TNF-α), and prostaglandin E2, which are elevated in periodontal disease." (PMID 38075042, 2023). "(i) If IL-1β, IL-6, AND TNF-α are elevated in the serum of patients with periodontal disease OR COVID-19 infection." (PMID 37106750, 2023). "This phenomenon is of clinical relevance since the treatment duration of TNF inhibitors can be a significant factor that influences the clinical outcomes in periodontal diseases." (PMID 36845132, 2023). "The cytokine TNF-α is another pro-inflammatory mediator in periodontal disease that is produced primarily by activated macrophages in response to infection." (PMID 37623272, 2023). "In periodontal diseases, TNF plays a major role as an osteoclast-stimulating hormone that mediates bone resorption via two distinct pathways: receptor activator of NF-ĸB ligand (RANKL) dependent and RANKL independent." (PMID 36845132, 2023). "Similar results have also been reported from further studies with a higher level of TNF-α in the serum of patients with AD and periodontal disease." (PMID 37214190, 2023). "Previous studies showed that IL-4 acts to improve periodontal disease through its regulatory potential against IL-1 and TNF-α and its ability to induce the death of activated macrophages." (PMID 37026605, 2023). "This scoping review highlights the immune-related similarities between the COVID-19 infection and periodontal disease, especially focusing on serum cytokine levels, such as IL-1β, IL-6, and TNF-α levels." (PMID 37106750, 2023). "TNF-α is the main connector to higher destructive periodontal disease and is the key pathogen to early inflammatory cytokines." (PMID 35830121, 2022). "Given that the production of proinflammatory cytokines lies at the heart of periodontal diseases, we next utilized qRT–PCR and ELISA to examine the mRNA levels of TNFα, IL-6, and IL-1β in gingival tissues and related protein levels in mouse serum." (PMID 35588785, 2022). "A pregnant woman with diagnosed periodontal disease had increased levels of IL-2, IL-4, IL-6, IL-10, TNF-α and INF-γ." (PMID 35055157, 2022). "Rothia antigens can activate lymphocytesin patients with periodontal disease, and induce tumor necrosis factor α (TNF-α) production in macrophages." (PMID 35873770, 2022). "TNF-α promotes the breakdown of alveolar bones by facilitating osteoclast production and host immune response, thereby accelerating the progression of periodontal diseases." (PMID 35409556, 2022). "Proinflammatory signaling activated by TNF-α is an important factor in the pathology of periodontal disease." (PMID 35200250, 2022). "In our previous study, the mRNA levels of ADAM17, which is related to the production of TNF-α, sTNF-R1, and sTNF-R2, were shown to be higher in the oral buccal mucosal epithelium according to the severity of periodontal diseases." (PMID 35200250, 2022). "Pro-inflammatory cytokines and chemokines, comprising IL-1 β, IL-6, and TNF-α, create an environment that fosters periodontal disease progression by affecting the balance in chronic inflammation." (PMID 34460002, 2022). "The findings of this study are the first step in clarifying the dynamics and roles of TNF-α, sTNF-R1, and sTNF-R2 in the process of periodontal disease." (PMID 35200250, 2022). "Similar inflammatory mediators, such as interleukin-6, tumor necrosis factor-alpha, and C-reactive protein, are increased in patients with severe periodontal disease." (PMID 36361416, 2022). "Proinflammatory mediators expressed in the rheumatoid synovium such as IL-6, TNF-α, transglutaminase 2, and inflammasome Nlrp3 have also been detected in saliva and serve as biomarkers for periodontal disease." (PMID 36506787, 2022).